RN7SKP60 (RN7SK pseudogene 60)
Gene: Miscellaneous RNA gene on chromosome 5 (165,609,441 to 165,609,679, forward strand). Ensembl gene ENSG00000252794.
Homologues: Orthologues: chimpanzee 7SK (99% identical), guinea pig 7SK (63% identical), guinea pig 7SK (62% identical), guinea pig 7SK (60% identical), guinea pig 7SK (57% identical), guinea pig 7SK (56% identical), guinea pig 7SK (52% identical), mouse Gm55912 (50% identical). Paralogues in human: 7SK (77% identical), RN7SKP80 (76% identical), RN7SKP131 (74% identical), RN7SKP176 (74% identical), RN7SKP203 (74% identical), RN7SKP221 (74% identical), RN7SKP255 (74% identical), RN7SKP63 (74% identical), RN7SKP75 (74% identical), RN7SKP9 (74% identical), RN7SKP130 (74% identical), RN7SKP217 (74% identical), and 284 more.